ADH5 (alcohol dehydrogenase 5 (class III), chi polypeptide)
Diseases named in the same sentence as ADH5 in open-access papers (continued):
Sharing a sentence is not in itself a finding about the gene and the disease.
clear cell renal cell carcinoma (1 paper, 2024). "The study found that ADH5 was under-expressed in various tumors, including renal clear cell carcinoma, through pan-cancer profiling." (PMID 38600527, 2024). "However, to the best of our knowledge, none of the researchers have carried out an in-depth study on the role of ADH5 in clear cell renal cell carcinoma." (PMID 38600527, 2024).
colorectal carcinoma (1 paper, 2022). A malignant epithelial neoplasm that arises from the colon or rectum and invades through the muscularis mucosa into the submucosa. "To further corroborate this observation, we inactivated the ADH5 gene in the non-blood derived human colorectal carcinoma cell line HCT116 by CRISPR/Cas9." (PMID 35136057, 2022).
ductal carcinomas (1 paper, 2023). "This study aimed to evaluate the diagnostic utility of the ADH5 cocktail stain in low-grade ductal carcinomas by assessing the visual ease of interpretation based on the chromogen and antibody composition." (PMID 37761331, 2023).
Glucose intolerance (1 paper, 2025). Glucose intolerance (GI) can be defined as dysglycemia that comprises both prediabetes and diabetes. "Of note, the glucose intolerance in 3-month-old Adh5BKO mice was comparable to 12-month wildtype mice, indicating a potential for accelerated age-reduced metabolic function in mice with BAT Adh5 deletion." (PMID 40631281, 2025).
invasive breast carcinoma (1 paper, 2023). A carcinoma that infiltrates the breast parenchyma. "We reviewed the ADH5 cocktail staining of low-grade invasive breast carcinoma (NOS) and tubular carcinomas to address this issue." (PMID 37761331, 2023).
invasive carcinoma (1 paper, 2023). A carcinoma that is not confined to the epithelium, and has spread to the surrounding stroma. "This study’s aim was to assess the usefulness and interpretability of the ADH5 multiplex stain in invasive carcinoma cases that were previously diagnosed." (PMID 37761331, 2023). "The positive staining of 34betaE12 in low-grade invasive carcinoma that is stained unexpectedly by ADH5 may be attributed to alterations in cytokeratin expression or antigen accessibility within the tumor microenvironment." (PMID 37761331, 2023). "The unexpected ADH5 staining pattern observed in invasive carcinomas and low-grade cytological atypia may lead to a misdiagnosis due to the resemblance to benign glands." (PMID 37761331, 2023).
liver dysfunction (1 paper, 2025). "However, Adh5-/-Fancd2-/- mice, which accumulate high levels of endogenous ICLs, do develop liver dysfunction and cancer." (PMID 40684071, 2025).
liver failure (1 paper, 2025). A liver disease characterized by the liver losing or has lost all of its function. "Conversely, Adh5-/-Csb-/- mice, deficient in TCR, develop kidney but not liver failure, suggesting the liver may rely more on replication-coupled repair, while the kidney depends on TCR." (PMID 40684071, 2025).
melanoma (1 paper, 2023). A malignant, usually aggressive tumor composed of atypical, neoplastic melanocytes. "Unexpectedly, ADH5 was significantly upregulated in primary melanoma samples of one dataset and showed an increasing trend in melanoma in the other two datasets (left)." (PMID 36831600, 2023).
osteoporosis (1 paper, 2021). A condition of reduced bone mass, with decreased cortical thickness and a decrease in the number and size of the trabeculae of cancellous bone (but normal chemical composition), resulting in increased fracture incidence. "Recent studies have found that excessive formaldehyde directly leads to muscle atrophy and osteoporosis in the mice with double-knockout of ADH5 and ALDH217,18." (PMID 34413463, 2021).
osteosarcoma (1 paper, 2022). A usually aggressive malignant bone-forming mesenchymal neoplasm, predominantly affecting adolescents and young adults. "We developed a new prognostic risk model for osteosarcoma based on 7 glycolytic genes (INSR, FAM162A, GLCE, ADH5, G6PD, SDC3, HS2ST1) by bioinformatics." (PMID 36387908, 2022). "A risk model based on seven glycolytic genes (INSR, FAM162A, GLCE, ADH5, G6PD, SDC3, HS2ST1) can effectively evaluate the prognosis of osteosarcoma, and in vitro experiments also confirmed the important role of INSR in promoting OS migration." (PMID 36387908, 2022).
tubular carcinomas (1 paper, 2023). "During our routine use of the ADH5 cocktail stain, an unexpected staining pattern was observed in low-grade infiltrating duct carcinoma (NOS) cases with tubular features and more so in tubular carcinomas." (PMID 37761331, 2023).
vitamin A deficiency (1 paper, 2016). Deficiency of vitamin A due to malnutrition, malabsorption, or dietary lack. "Mice with Adh7 (formerly Adh4) mutation are hypersensitive to vitamin A deficiency, and mice with a mutation of Adh5 (formerly Adh3) are hypersensitive to both excess and deficiency of vitamin A." (PMID 27983671, 2016).
tumor (22 papers, 2012 to 2025). "In terms of tumor immune cell infiltration, ADH5 was significantly associated with B-cell, CD8 + T-cell, and macrophage infiltration (all P < 0.001)." (PMID 38600527, 2024). "From an immunological perspective, ADH5 was found to be associated with the tumor microenvironment, immune cell infiltration, and immune checkpoints." (PMID 38600527, 2024). "Studies indicate that this gene is activated constitutively in malignant tumors and the action of some molecules with anti-tumor activity is attributed to the inactivation of this factor; a group of genes encoding alcohol dehydrogenases (Adh1, Adh5, Adh6a, Adh6b, Adh7) maps at 138 Mb." (PMID 34966170, 2022). "Our analysis of the TIDE database indicates that KIRC patients with high ADH5 expression have higher tumor immune dysfunction scores." (PMID 38600527, 2024). "Metabolic genes CYP1B1, AANAT, ADH5, and ALDH3A2, associated with the serotonin and melatonin biosynthesis pathway, contribute to tumour growth, immune modulation, and altered metabolic states in the TME." (PMID 39457550, 2024). "From these results, we conclude that reduced ADH5 expression in KIRC patients correlates with tumor progression." (PMID 38600527, 2024). "While the expression level of ADH5 was remarkably increased with the progression of tumor malignancy." (PMID 33287761, 2020). "Although, a recent study reported that decreased ADH5 expression in HBV-related HCC tumor tissue predicted earlier recurrence." (PMID 33287761, 2020). "ADH5 was expressed at the S351 phosphorylation site in tumor tissues with an altered mTOR pathway." (PMID 38600527, 2024). "HCT116 ADH5-deficient cells were sensitive to FA and were not able to form tumour-spheroids when exposed to FA." (PMID 35136057, 2022). "Immunohistochemical results from the HPA database on ADH5 expression in KIRC and the CPTAC dataset on ADH5 expression in normal and KIRC tumor tissues were consistent with these results." (PMID 38600527, 2024). "ADH5, NUDT7, PTGES3, D2HGDH, HAO2 and CPT1C also play regulatory roles in the pathological processes of various tumours." (PMID 36643625, 2023). "Considering that inhibition of Polθ is synthetically lethal in HR-deficient malignant cells, we speculated that inhibition of ADH5 and/or ALDH2 may enhance this anti-tumor effect." (PMID 40640557, 2025). "Concurrently, the expression of ADH5 in tumor tissue was significantly lower compared to the adjacent normal tissue (P < 0.001)." (PMID 38600527, 2024). "Finally, seven prognostic genes-ADH5, FAM162A, HS2ST1, INSR, G6PD, GLCE, and SDC3-were found to have the strongest correlation with tumor metastasis." (PMID 38586328, 2024). "Studies have shown that ADH5 and ADH7 may play an anti-tumor role in the carcinogenesis of Non-small cell lung cancer (NSCLC) and can be used as biomarkers to predict NSCLC patients." (PMID 36387908, 2022). "However, three glycolysis-related genes (ADH1B, ADH5, and NUP210) were significantly differentially expressed at the mRNA level in tumor tissues versus adjacent normal tissues but were not significantly related to patient prognosis (p > 0.05)." (PMID 34595101, 2021). "In addition, our GSEA results also showed that high expression group of ADHs was significantly and negatively associated with pathways in cancer without ADH5, which suggested that high expression of ADHs could inhibit cancer related pathways and ADHs presented the tumor suppressor role." (PMID 33287761, 2020). "By summarizing all the points, ADHs without ADH5 might act as the tumor suppressor via inhibiting oncogenic signaling pathway in HCC." (PMID 33287761, 2020).
cancer (21 papers, 2012 to 2025). A tumor composed of atypical neoplastic, often pleomorphic cells that invade other tissues. "Currently, in the field of oncology, there are also numerous studies showing a close association between ADH5 and cancer." (PMID 38600527, 2024). "As a member of the alcohol dehydrogenase (ADH) family, ADH5 is a relevant player in inflammation, immune regulation, and cancer progression, as well as many other processes, and its dysregulation can upset cellular homeostasis and cause disease." (PMID 38600527, 2024). "In Nalm6 cells, which grow in suspension, the treatment with L-BSO increased the sensitivity of ∆ADH5 cells to FA, suggesting that GSH biosynthesis and ADH5 independently contribute to prevent FA toxicity in this lymphoblastic human cancer cell line." (PMID 35136057, 2022). "In addition to this, researchers have found that ADH5 acts as a player in cancers such as breast, ovarian, and prostate cancers." (PMID 38600527, 2024). "By using ADH5, pathologists can better identify the presence of carcinoma in biopsy samples." (PMID 37761331, 2023). "And the low expression group of ADHs family members not including ADH5 was significantly but negatively associated with pathways in cancer." (PMID 33287761, 2020). "We show that NAC lowered DNA damage and improved growth of ADH5−/− keratinocytes, in both an FA-competent and FA-deficient setting, confirming the potential of aldehyde scavengers, particularly for formaldehyde and LPO-derived aldehydes, as cancer prevention strategy." (PMID 41292832, 2025). "Besides, the genetic ADH5 and ALDH2 deficiency in mice, a condition common among humans, leads to increased circulating levels of formaldehyde, which might then affect the bone marrow and cause cancer in the lymphatic tissue and solid organs." (PMID 41146278, 2025). "Ongoing efforts are focused on developing mouse models that spontaneously develop oral SCCs, which will enable mechanistic studies to confirm the protective roles of ADH5 and ALDH3 enzymes in maintaining genome stability and preventing cancer development." (PMID 41292832, 2025). "However, the sensitivity of ADH5 in identifying low-grade carcinomas has not been thoroughly investigated." (PMID 37761331, 2023).
infection (11 papers, 2019 to 2025). The state of being infected such as from the introduction of a foreign agent such as serum, vaccine, antigenic substance or organism. "In the present study, we showed that pathogen infection facilitated S-nitrosylation of STING to suppress host defense by downregulating ADH5 expression." (PMID 38409248, 2024). "We found that pathogens infection lost the inhibitory effects on ADH5 expression in Azacitidine treated macrophages." (PMID 38409248, 2024). "Therefore, ADH5 is downregulated during pathogens infection to circumvent STING-dependent type I IFN responses by modulating SNO homeostasis." (PMID 38409248, 2024). "Our results reveal the mechanism by which oxidative burst, the physiological process that occurs during pathogen infection, regulates innate immune responses and suggest that SNO homeostasis maintained by ADH5 is required for STING activation." (PMID 38409248, 2024).
bacterial infection (1 paper, 2024). "Adh5 deficiency triggers substantial increases in whole-cell S-nitrosylation during bacterial infection, resulting in enhanced tissue damage and lymphocyte apoptosis." (PMID 38409248, 2024).
hematological disorders (1 paper, 2024). "In a total of 417 samples with IBMFS or associated hematological disorders, targeted proteomic analysis was found to provide a simple and direct diagnostic contribution for both patients with SDS and ADH5/ALDH2 deficiency." (PMID 38740980, 2024).
ADH5 also shares sentences with these, for which no sentence is quoted: asthma (8 papers); amyotrophic lateral sclerosis (4); cystic fibrosis (4); airway hyperresponsiveness (3); cardiac hypertrophy (3); Insulin resistance (3); Myelodysplasia (3); viral infection (3); alcoholic liver diseases (2); allergic asthma (2); atherosclerosis (2); cardiac ischemia (2); COVID-19 (2); diabetes (2); dwarfism (2); Hypertension (2); lung disease (2); muscular dystrophies (2); myocardial infarction (2); neurodegenerative disease (2); ovarian carcinoma (2); Parkinson disease (2); prostate carcinoma (2); Xeroderma pigmentosa (2); acute lymphoblastic leukemia (1); acute monocytic leukemia (1); acute myeloid leukaemia (1); adenocarcinoma (1); Alzheimer disease (1); autism spectrum disorder (1).
A further 51 diseases each share a sentence with ADH5 in 1 paper.